EYA1 (EYA transcriptional coactivator and phosphatase 1)
Diseases named in the same sentence as EYA1 in open-access papers (continued):
Sharing a sentence is not in itself a finding about the gene and the disease.
multicystic dysplastic kidney (2 papers, 2020 to 2021). Multicystic dysplastic kidney (MCDK) is a congenital anomaly of the kidney and urinary tract (CAKUT) in which one or both kidneys (unilateral or bilateral MCDK respectively) are large, distended by multiple cysts, and non-functional. "Renal phenotypes of mutations in HNF1B, PAX2, and EYA1 were bilateral renal hypodysplasia or unilateral renal hypodysplasia with contralateral multicystic dysplastic kidney." (PMID 32164334, 2020).
renal hypoplasia (2 papers, 2008 to 2021). Renal hypoplasia is a developmental anomaly in which one or both kidneys (unilateral or bilateral renal hypoplasia, respectively) have a deficit in the number of nephrons and may be small. "Mutations in EYA1 cause the Mendelian syndrome branchiootorenal dysplasia syndrome (MIM# 113650) featuring a renal phenotype ranging from mild renal hypoplasia to complete absence of the kidneys." (PMID 18522750, 2008).
brain tumor (1 paper, 2021). "Compared with other types of brain tumor, meningioma has significantly higher expression of EYA1." (PMID 33807688, 2021).
chronic otitis media (1 paper, 2022). Chronic form of otitis media (disease). "Here, we characterize the onset, consequences, and underlying causes of chronic otitis media in Eya1 heterozygous mice." (PMID 36299576, 2022).
clear cell renal cell carcinoma (1 paper, 2023). "In conclusion, the results imply that EYA1/3 transcriptional expression plays an independent prognostic role in clear cell renal cell carcinoma." (PMID 37156847, 2023).
colon cancers (1 paper, 2026). "Small, but significant increases were also seen for the transcription factor EyA1, which is implicated in the activation of cell proliferation and EMT in colon cancers." (PMID 41576101, 2026).
epilepsy (1 paper, 2021). A brain disorder characterized by episodes of abnormally increased neuronal discharge resulting in transient episodes of sensory or motor neurological dysfunction, or psychic dysfunction. "Interestingly, we observed that when compared to the normal controls, the expression of some identified genes was only significantly altered either in Epilepsy (EGLN1, ELAVL4, and NFE2l2) or Hemorrhage (USP22, EYA1, SIX1, OAS3, SRMS) groups." (PMID 34588521, 2021).
fibrosis (1 paper, 2022). the formation of excess fibrous connective tissue in an organ or tissue in a reparative or reactive process. "While the promoter of the Nsf (nephrogenic system fibrosis) gene was co-occupied by Eya1/Six2, Six2 alone also bound to a distal intronic CRE/enhancer ∼+70-kb, and Eya1 alone occupied another distal intronic CRE ∼+35-kb without H3k27ac-deposition but with two REST motifs." (PMID 36130284, 2022).
ganglioneuroblastoma (1 paper, 2016). A neuroblastic tumor characterized by the presence of neuroblastic cells, ganglion cells, and a stroma with Schwannian differentiation constituting more than fifty-percent of the tumor volume. "We found that EYA1 levels were significantly higher in neuroblastomas than in ganglioneuromas and ganglioneuroblastomas." (PMID 28713571, 2016). "This is also consistent with the predominantly cytoplasmic localization of EYA1 in non- and less malignant ganglioneuromas and ganglioneuroblastomas." (PMID 28713571, 2016). "In contrast, all of the ganglioneuromas (n=3) and 7 of 8 ganglioneuroblastomas showed negative or low EYA1 protein expression, while one ganglioneuroblastoma showed high EYA protein expression." (PMID 28713571, 2016).
gastric ulcer (1 paper, 2021). An ulcerated lesion in the mucosal surface of the stomach. "Expression of EYA1 was lower at the gastric ulcer edge when compared with the antrum." (PMID 34864618, 2021).
hypoparathyroidism (1 paper, 2020). Hypoparathyroidism is an endocrine disorder in which the parathyroid glands in the neck do not produce enough parathyroid hormone (PTH). "In other words, because EYA1 is necessary for parathyroid development and played a role in the angiogenic procedure, if ADSC could be induced differentiating into parathyroid cells, it could be a perfect resource for clinical employment in the treatment of hypoparathyroidism." (PMID 32456711, 2020).
kidney cancer (1 paper, 2023). Primary or metastatic malignant neoplasm involving the kidney. "The level of mRNA of EYA1 was highly expressed in kidney cancer, while EYA2/3/4 was expressed low in cancer tissues with adjacent normal tissues (respectively)." (PMID 37156847, 2023). "After identifying a significant correlation between mRNA expression of EYA1/3/4 and the prognosis of kidney cancer patients, we conducted a multivariate Cox regression analysis using the TCGA dataset to determine whether mRNA expression of EYA1/3/4 could independently predict patients' prognosis." (PMID 37156847, 2023). "Thus, EYA1/3/4 proteins could serve as potential targets for kidney cancer therapy and prognostic markers for improving patient survival and accuracy." (PMID 37156847, 2023).
lymph node metastasis (1 paper, 2019). "Higher levels of SIX1 and EYA1 were found correlated with advanced age and lymph node metastasis, which are well-known poor prognostic factors in PTC." (PMID 31921695, 2019).
melanoma (1 paper, 2017). A malignant, usually aggressive tumor composed of atypical, neoplastic melanocytes. "Further, EYA1 reduction in melanoma cells caused reduction of its phosphatase function as a result of increased phosphorylation of histone γH2AX." (PMID 29285235, 2017). "In conclusion, EYA1 gene is a pathogenic driver in melanoma pathogenesis." (PMID 29285235, 2017). "Finally, treatment with benzbromarone, a specific inhibitor of EYA1, caused significant inhibition of melanoma cell proliferation, and increased sensitivity to the BRAF inhibitor vemurafenib." (PMID 29285235, 2017). "Our results showed that EYA1 protein is low in benign nevi, but is significantly up-regulated in melanoma in situ, and remains high in invasive and metastatic melanoma." (PMID 29285235, 2017). "Melanoma cells with down-regulated EYA1 had much lower levels of cellular growth rate, decreased colony formation, and reduced DNA synthesis." (PMID 29285235, 2017). "These suggest that EYA1 upregulation primarily altered rate of cellular proliferation in melanoma cells." (PMID 29285235, 2017). "Further, EYA1 gene silencing and inhibition significantly decreased proliferation of melanoma cells." (PMID 29285235, 2017). "The results presented in this study showed that EYA1 upregulation occurred early in the malignant transformation of melanoma cells, starting as early as in melanoma in situ stage during radial growth phase." (PMID 29285235, 2017). "To further demonstrate the therapeutic implications of EYA1 in melanoma, we tested if chemical inhibitor of EYA1 has any effects on the proliferation of melanoma cells." (PMID 29285235, 2017). "The expression was low in BN and DN, but was dramatically upregulated in MIS, and remained high in PM and MM, indicating that EYA1′s aberrant expression is initiated during the malignant transformation step of melanoma progression." (PMID 29285235, 2017). "Melanoma tissue microarrays were used to assess EYA1 protein expression in 326 melanoma tissues, and to correlate the expression with patients’ clinical pathological parameters." (PMID 29285235, 2017). "Our results revealed that EYA1 may be a valuable target for developing novel therapies of melanoma, which, despite the recent significant therapeutic developments, still carries high mortality." (PMID 29285235, 2017). "One of these genes is EYA1, which is found to be over expressed in melanoma transcriptome analysis." (PMID 29285235, 2017). "We next examined the status of the down-stream molecular changes in EYA1-silenced melanoma cells." (PMID 29285235, 2017). "Our results revealed that EYA1 expression is associated with malignant transformation of melanoma cells but not that of keratinocyte malignancies." (PMID 29285235, 2017). "EYA1 is a DNA repair enzyme that is induced after DNA damage and is upregulated in melanoma." (PMID 29285235, 2017). "In addition, retroviral ShRNA vectors were used to silence expression of EYA1 in A375 melanoma cells, and the resultant cells examined for changes in growth, DNA synthesis, and tumor formation in vitro." (PMID 29285235, 2017). "Targeting EYA1 may be a valuable strategy for treatment of melanoma." (PMID 29285235, 2017). "In conclusion, our study showed significant aberrant upregulation of EYA1 phosphatase early in the melanoma transformation process, and that inhibition of this enzyme either by gene silencing or by chemical agents leads to inhibition of melanoma cell proliferation." (PMID 29285235, 2017). "Therefore, EYA1 signaling pathway may represent an attractive target for developing melanoma therapies in the future." (PMID 29285235, 2017). "We next examined if the expression of EYA1 in melanoma biopsies is preserved in cultured melanoma cells by comparing the expression of EYA1 mRNA in cultured primary melanocytes (HEMC) and patient-derived melanoma cell lines (MMC)." (PMID 29285235, 2017).
melanoma (continued). "To further investigate the clinical relevance of EYA1 protein expression, we performed regression analysis between EYA1 expression intensity and patient's age, gender, AJCC staging, tumor thickness, mitotic rate, melanoma subtypes, and other clinical pathological parameters." (PMID 29285235, 2017).
meningioma (1 paper, 2021). A generally slow growing tumor attached to the dura mater. "Our results support the critical role of EYA1 in meningioma though further investigation is required to validate altered activated pathways caused by EYA1 fusion." (PMID 33807688, 2021). "Although our study fails to identify the subtype or recurrence specific biomarkers, we discovered that gene fusion with EYA1 is the most common fusion across all subtypes of meningioma, indicating EYA1 fusion is likely an early event in tumorigenesis in meningioma." (PMID 33807688, 2021). "In meningioma, EYA1 is also a key molecule by regulating the cell viability and cell cycle." (PMID 33807688, 2021).
neuroblastoma (1 paper, 2016). Neuroblastoma (NB) is the most common solid, extracranial childhood tumor. "But the potential association between nuclear localization of EYA1 and advanced stage of neuroblastomas will be followed up in future studies to understand and confirm this relationship." (PMID 28713571, 2016). "In support of this model, we also found high EYA1 protein levels in stage 4S neuroblastoma specimens, a stage of disease associated, by definition, with young infants, and uniquely at high likelihood of spontaneous regression." (PMID 28713571, 2016). "High EYA1 mRNA levels were associated with good prognosis, whereas low EYA1 expression was associated with poor outcome in the Versteeg dataset consisting of a cohort of 88 neuroblastoma patients." (PMID 28713571, 2016). "Our study extends the previous findings to human neuroblastoma cells and shows the association of nuclear EYA1 with nuclear MYCN in both human neuroblastoma cell lines and primary neuroblastoma tumors." (PMID 28713571, 2016). "Our analysis of EYA1 subcellular localization in neuroblastomas suggested an association between nuclear localization and high-risk tumors, although this small sample size did not permit attainment of statistical significance." (PMID 28713571, 2016). "We utilized immunohistochemistry to examine the expression patterns of EYA1 in tissue microarrays (TMAs) composed of tissue samples collected from 98 individual patients, including 66 cases of neuroblastoma, and looked for correlation with standard-risk determining diagnostic factors." (PMID 28713571, 2016). "This study provides several lines of evidence for a relationship between EYA1 expression and the biology and clinical behavior of neuroblastoma." (PMID 28713571, 2016). "Since EYA1 has a known role in neurogenesis during development and EYA homologs, including EYA1, have recently been linked to other paediatric malignancies, we investigated the expression of EYA1 in neuroblastoma." (PMID 28713571, 2016). "While further studies are needed to confirm this observation, these results suggest a mechanistic basis for the prevalence of EYA1 nuclear localization in advanced neuroblastoma tumors." (PMID 28713571, 2016). "Our results show that EYA1-postive neuroblastoma tumors were more likely diagnosed in children with stage 1,2,3 and 4S disease." (PMID 28713571, 2016). "Taken together, our analyses of 2 independent mRNA microarray datasets and the Children’s Oncology Group TMAs suggest EYA1 as a novel prognostic marker in neuroblastoma." (PMID 28713571, 2016). "To determine the relationship of differentiation and, as a surrogate for it, proliferation index to EYA1 expression in neuroblastomas, we examined EYA1 protein immunostaining as a function of favourable versus unfavourable histology and MKI, respectively." (PMID 28713571, 2016). "Second, high EYA1 mRNA levels are prognostic for favorable outcome in 2 independent gene expression datasets that collectively examine tumors from 564 neuroblastoma patients." (PMID 28713571, 2016). "We confirmed that high EYA1 mRNA levels are prognostic for favorable outcome with the Kocak dataset, which includes a cohort of 476 neuroblastoma patients." (PMID 28713571, 2016). "We then tested the hypothesis that nuclear EYA1 levels are correlated with MYCN levels in primary neuroblastoma tumor specimens." (PMID 28713571, 2016). "To test the hypothesis that nuclear EYA1 predominates in advanced stage neuroblastoma, we scored the TMA specimens with high EYA1 expression (41 in total) for cytoplasmic and nuclear EYA1 localization." (PMID 28713571, 2016). "To extend our studies to protein levels of EYA1, we stained neuroblastoma TMAs for EYA1." (PMID 28713571, 2016). "EYA1 staining correlates inversely with advanced neuroblastoma stage." (PMID 28713571, 2016).
neuroblastoma (continued). "Furthermore, as high nuclear MYCN levels are closely related to advanced stage neuroblastomas, we propose that the correlation between high-level nuclear MYCN and nuclear localization of EYA1 would mainly occur in advanced stage neuroblastomas." (PMID 28713571, 2016). "Based on recent findings that EYA1 activity is regulated by post-translational modifications, further studies on the function and (dys)regulation of EYA1 in neuroblastoma and other malignancies are critical to the potential exploration of EYA1 as a target for cancer therapy and drug development." (PMID 28713571, 2016). "Therefore we then investigated the relationship of EYA1 mRNA expression to overall survival in neuroblastoma patients by performing Kaplan-Meier analysis of survival for the publicly available neuroblastoma datasets." (PMID 28713571, 2016). "We studied EYA1 expression and subcellular localization by immunohistochemistry in tissue microarrays containing tumor specimens from 98 patients, 66 of which were characterized by known clinical prognostic markers of neuroblastoma." (PMID 28713571, 2016). "Modulation of expression and subcellular localization of EYA1 in neural crest cells may provide novel therapeutic strategies for neuroblastoma." (PMID 28713571, 2016). "We conclude that EYA1 may be a potential biomarker for neuroblastoma prognosis, and modulation of its expression and subcellular localization in neural crest cells may contribute to the therapy of neuroblastoma." (PMID 28713571, 2016). "Whether or not EYA1 is implicated in neuroblastoma and subcellular localization of EYA1 is relevant to clinical behaviour of neuroblastoma is not known." (PMID 28713571, 2016). "We then examined whether endogenous MYCN forms a complex with EYA1 in neuroblastoma cells." (PMID 28713571, 2016). "In this series of 66 neuroblastomas, 41 showed a high-level of EYA1 protein expression and 25 showed negative or low EYA1 expression." (PMID 28713571, 2016). "Importantly, our results demonstrated a physical interaction between EYA1 and nuclear MYCN, a classical oncogenic transcription factor and major driver of neuroblastoma tumorigenesis, in both transfected human embryonic kidney cells and native neuroblastoma cells." (PMID 28713571, 2016). "However, the relationship between EYA1 and MYCN in the context of neuroblastoma has not been explored." (PMID 28713571, 2016).
otitis media (1 paper, 2022). Inflammation of the anatomical structures of the middle ear, which is most often caused by an infectious process. "The onset of otitis media in the Eya1 heterozygous mice was followed through a postnatal developmental series." (PMID 36299576, 2022). "Eya1 was shown to be expressed in postnatal tissues, but the changes observed in the epithelium were linked to the consequence of otitis media rather than a direct effect of a reduction in Eya1 expression." (PMID 36299576, 2022). "Given the expression of Eya1 in the hypotympanum and ET at P7, we examined whether the distribution of cilia and secretory cells was normal in the mutants at this stage, prior to the onset of otitis media." (PMID 36299576, 2022).
peptic ulceration (1 paper, 2021). "In conclusion, we have identified that common genetic variants in the EYA1 gene predispose to aspirin-induced peptic ulceration." (PMID 34864618, 2021). "Mechanistic knowledge of the role of EYA1 in aspirin-induced peptic ulceration may also allow the development of new agents for preventing PUD." (PMID 34864618, 2021).
prostate carcinoma (1 paper, 2023). A carcinoma that arises from epithelial cells of the prostate gland. "We observed enrichment of mutations in several genes including understudied genes such as EYA1, CSMD3, FLT4, NCOR2, and PCDH15 and found that mutations in EYA1 and CSMD3 are associated with a poor outcome in prostate cancer." (PMID 38067373, 2023). "Future directions for this work include further characterization of EYA1, CSMD3, FGFR3, and PCDH15 in prostate cancer metastases and the roles of oxidative phosphorylation and FGFR3 in prostate cancer health disparities." (PMID 38067373, 2023).
prostate tumors (1 paper, 2023). "Integrative genomic analysis of primary prostate tumors and associated LNM demonstrated the enrichment of mutations in several genes including both well-established oncogenes and tumor suppressors and understudied genes such as EYA1, CSMD3, FLT4, NCOR2, and PCDH15." (PMID 38067373, 2023).
respiratory failure (1 paper, 2022). The significant impairment of gas exchange within the lungs resulting in hypoxia, hypercarbia, or both, to the extent that organ tissue perfusion is severely compromised. "Mice deficient in Eya1–/– and Eya2–/+ have no diaphragm, whereas single mutant Eya1 mice die shortly after birth due to respiratory failure, having severely hypoplastic lungs with reduced epithelial branching and increased mesenchymal cellularity." (PMID 35633948, 2022).